CD4 (CD4 molecule)
Diseases named in the same sentence as CD4 in open-access papers (continued):
Sharing a sentence is not in itself a finding about the gene and the disease.
tumor (continued). "Intraneoplastic inoculation of dvB7Ig/G207 in the neuroblastoma syngeneic mouse model inhibited the cancer progression and substantially increased CD4+ and CD8+ T cell infiltration, and the mice cured by dvB7Ig/G207 treatment were protected against tumor rechallenge." (PMID 36755812, 2022). "IHC staining indicated that CXCL13 was not expressed in tumor cells but was detected intensively in TLSs and CD4+ TFH cells." (PMID 35053457, 2022). "IL-33/ST2 signaling suppresses IL-17A production and potentially promotes the conversion of IL-17-producing CD4+ T cell types to IL-17-negative (RORγt−) ST2+ FOXP3+ Treg cells, modifying the inflammatory signals within the tumour microenvironment to promote CRC." (PMID 36569832, 2022). "In particular, CD4 + T-helper 1 (Th1) cells facilitate antigen presentation through cytokine secretion and activation of antigen presenting cells, while CD8 + cytotoxic T-cells (CTL) are essential for tumour destruction." (PMID 35248020, 2022). "To test the CD4-mediated antitumor effect, we transferred CD4 T cells from the Marilyn anti H-Y TCR transgenic mouse (which has no CD8 T cells) into nonimmunized tumor-bearing B6 mice." (PMID 35903540, 2022). "Even though all CD4 T cell subsets increase following vaccination including Tregs when normalized using cell count per mg tumor (data not shown), some T cell subsets expand much more than others." (PMID 36569934, 2022). "When we classified a series of PDS tumors into immunologically hot and cold tumors (high versus low amounts of both CD4/CD8+ cells and high versus low PD-L1 expression), we did not detect a significant difference of tumor mutational burden (TMB)." (PMID 36465341, 2022). "HA-man@Fe3O4 alone failed to stimulate the promotion of CD4+ T cells, indicating the necessity of tumor-specific peptides in the infiltration of CD4+ T cells." (PMID 36291890, 2022). "PSMB8 could be detected with a relatively high expression in various immune cells and tumor cells, and PLAAT4 showed a relatively high expression in CD4+ T cells, CD8+ T cells, NK cells, and proliferative T cells." (PMID 36072600, 2022). "In another, which also included the GVAX anti-tumor vaccine, the anti-CSF-1R antibody given with anti-PD-1 therapy increased the number of intratumoral PD-1+ CD8+ and PD-1+ CD4+ T cells and increased their expression of IFNγ, a cytokine known to stimulate NK cells and neutrophils." (PMID 36077755, 2022). "Amongst T cells, CD4+ helper and CD8+ cytotoxic T cells enact immune surveillance, recognition, and destruction of tumor cells while regulatory T cells (Treg) suppress anti-tumor immune responses." (PMID 36338744, 2022). "Nevertheless, DFNA5 expression had no pronounced association with tumour purity and enrichment of immune cells, including B cells, macrophages, neutrophils, CD8 + T cells, CD4 + T cells, or dendritic cells in HNSC." (PMID 35248047, 2022). "We postulate that cytotoxic CD4+ T cells exist in NSCLC and may function via HLA-II expression on tumor cells, which, when viewed collectively, could be a mechanistic basis for anti-tumor immune responses observed in HLA-I-disrupted tumors." (PMID 35831288, 2022). "In fact, GNP-LLO91–99 nanovaccines increased percentages of CD4+ and CD8+ T cells, B cells, and functional antigen-presenting DCs in tumor-infiltrated lymphocytes, while they reduced the levels of myeloid-derived suppressor cells (MDSC) and suppressor T cells (Treg)." (PMID 35626016, 2022). "In conclusion, the correlation of MSLN tumor antigen presentation and HLA-DRB gene expression with prolonged survival indicates a central role of CD4+ T-cell responses for tumor immune surveillance in OvCa, and highlights the importance of immunopeptidome-guided tumor antigen discovery." (PMID 35565389, 2022). "Normal CD4+ T lymphocytes corresponding to AITL tumor cells and the normal CD4+CD7- T-cell population in BM, PB and tissues were polyclonal." (PMID 36160159, 2022).
tumor (continued). "A comparison of the fractions of T cells expressing coinhibitory molecules in the UM TIL cultures with or without a response to autologous tumor cells showed no overt differences for CD8+ TILs or CD4+ TILs." (PMID 36249685, 2022). "In fact, ROCKi, combined with an anti-PD-1 antibody, decreased the growth of the anti-PD-1-resistant melanomas through both the intrinsic tumour’s cell death and the relief of immunosuppression, without affecting tumour infiltration by CD4+ or CD8+ T cells." (PMID 35159327, 2022). "While CD4+ T cells assist in B-cell maturation and are closely involved in cellular immunity, CD8+ T lymphocytes have cytotoxic activity and play a vital role in anti-tumor immunity." (PMID 36555814, 2022). "Neutralization of CD4+ or CD25+ T cells did not affect the antitumor efficacy of LP on tumor growth." (PMID 35764365, 2022). "In CD4+ T cell-depleted mice, acceleration of tumor growth was observed in CD-fed mice but not in HFD-fed mice." (PMID 36611881, 2022). "It has been shown that cDC1 are not capable of activating CD4+ T cells ex vivo, and that the antigenic presentation of cDC2 to CD4+ T cells regulates multiple aspects of tumor immune response." (PMID 35267487, 2022). "However, when spleen cells from vaccinated tumor bearing mice were stimulated with mCAR12/mCDK12 in the presence of the anti-TIGIT antagonist antibody, more CD4 and CD8 T cells produced IFN-γ as assessed by flow cytometry." (PMID 36569934, 2022). "Therefore, among CD3 + T cells, the numbers of CD3 + /CD8 + cytotoxic T cells and CD3 + /CD4 + helper T cells in tumor lesions of MB49 cell-implanted mice were evaluated by FACS and IHC analyses using antibodies to CD8, CD4, and FoxP3." (PMID 35787261, 2022). "In addition, exhausted CD4+ T cells, characterized by high expression of CXCL13 and BTLA, which are T follicular helper markers, were mainly collected from the tumour tissue." (PMID 35184398, 2022). "CD4+ T cells were the dominant population within the blood of both tumor-bearing and non-bearing mice treated with PBS." (PMID 35782876, 2022). "Finally, we evaluated the immune regulation of PCSP-AuNPs using a mouse model with H22-tumor by testing the index of immune organs, splenic lymphocyte proliferation, cytokines levels (TNF-α and IL-10), and the CD4+/CD8+ cell ratio in the peripheral blood." (PMID 35762637, 2022). "Notably, the proportion of the CD4+ helper T cells in the free 1-MT and 1-MT loaded groups decreased in the B16F10 tumor-bearing mice, which was consistent with the previously reported studies." (PMID 35577812, 2022). "No tumor infiltration of CD4+ or CD8+ T lymphocytes, macrophages, APCs, dendritic cells were observed 2 and 6 h after IRE." (PMID 35740542, 2022). "Even though we conducted other immune cell test including CD4+, Macrophage, Dendritic cells there were no significant affection in tumor regression." (PMID 36545214, 2022). "Treatment with Dex induced a significant decrease in CD4+ T cells (p < 0.05 vs. PBS no tumor) and a significant concomitant increase in CD8+ T cells (p < 0.01)." (PMID 35782876, 2022). "In addition, PD-1 inhibitors play an essential role in tumor immune escape by enhancing the function of CD8+ T cells and CD4+ Th cells and inhibiting the development of various tumors." (PMID 35942408, 2022). "For each patient, tumor cells (clonal TCRvβ or CD4‐positive cells) and normal cells used as individual controls (TCRvβ or CD4‐negative cells) were sorted and analyzed." (PMID 33715271, 2022). "Increased tumor cell death was observed following combination treatment and, in addition, the enzymatic dissociation of PCTS and subsequent flow cytometric analysis showed the increased presence of CD45+, CD8+ and CD4+ T cells after treatment combination." (PMID 35466279, 2022). "Additionally, tumor-specific MHC-II expression is correlated with the activation of IFNG pathway, higher levels of Th1 cytokines, and CD4+/CD8+ lymphocytes infiltration." (PMID 35350568, 2022).
tumor (continued). "Moreover, this combination regimen induced tumor infiltration of CD8+ and CD4+ T cells and increased the ratio of the anti-tumor M1 macrophages, while reducing both the number of Tregs cells and MDSCs." (PMID 35740542, 2022). "In a preclinical study using murine models, CD4+ cells are found to be recruited in the tumor microenvironment but not activated after BCG." (PMID 35992775, 2022). "In our study, the high‐index patients with LUAD had significantly higher proportions of neutrophils and resting memory CD4+ T cells, restricting the function of CD8+ T cells and NK cells in the tumour development process, resulting in malignant tumour progression and worse OS." (PMID 34877770, 2022). "Both CD4+ and CD8+ T cells were enriched in primary cSCC, while recurrent cSCC sites showed the lowest T cell infiltration, indicating that recurrent cSCC tended to be a T cell desert tumor." (PMID 36438481, 2022). "We found a significant difference between the two groups where the group showing a higher CD4 T-cell IFNγ expression had a lower tumor burden (responders) and the group with a lower CD4 T-cell IFNγ expression had a higher tumor burden (non-responders)." (PMID 35651802, 2022). "Positive correlations were observed between levels of different immune checkpoint-expressing CD4+ T cells, including PD-1, TIM-3, LAG-3, and CTLA-4 with FoxP3+ Tregs, Helios+ T cells, FoxP3+Helios+ Tregs, and FoxP3+Helios− Tregs in the tumor microenvironment (TME)." (PMID 35455287, 2022). "Notably, in addition to these treatment effects in the targeted tumor, we also found increased abundance of central memory T cells (CD44+CD62L+), CD44+ effector T cells and CD69+ activated T cells among CD4+ and CD8+ T cells in the TDLNs in PIC + RT group 45." (PMID 35999216, 2022). "As with targeting CD4, designing multipronged CAR-T cells under a subsequent “HELP” gate framework, where a CD47 CAR assists T cells to bind with tumor cells first, followed by the ligation of the second CAR with another target antigen, may be possible." (PMID 36059451, 2022). "Specific to MIF signaling in tumor tissue, CellChat identified ligand MIF and its multi-subunit receptor CD74+CXCR4 as the most significant signaling, contributing to the communication from CD4+ T cells to CD8+ T2 and CD8+ T3 cells." (PMID 35812372, 2022). "Furthermore, a higher infiltration of CD4+ and CD8+ T cells in the tumor regions was determined, which was correlated with a better survival outcome in the tumor-bearing mice." (PMID 36389666, 2022). "Thus, through the activation of CD4+ T and CD8+ T in response to cross-reactivity of bacterial antigens, T cell employ anti-tumor effects." (PMID 35600385, 2022). "Also, the expression levels of CFP were correlated with many sets of immune markers of tumor immune cells, such as those of CD8+ T cells, CD4+ T cells, B cells, M2 macrophages, neutrophils, DCs, Th1 cells, Th2 cells, and T cell exhaustion in HCC." (PMID 34813686, 2022). "We conducted in silico experiments to investigate how clinically relevant design choices and inherent tumor features—CAR T-cell dose, CD4+:CD8+ CAR T-cell ratio, CAR-antigen affinity, cancer and healthy cell antigen expression—individually and collectively impact treatment outcomes." (PMID 35903149, 2022). "pCR/MPR patients displayed significantly higher density of CD3+, CD3+CD4+, CD20+, CD56 bright cell subsets and more tertiary lymphoid structures and significantly lower density of PD-L1+CD68+ and CD3+CD4+Foxp3+cells in the tumor or stroma." (PMID 36275670, 2022). "In contrast, the anti-tumor efficacy of lactate was not affected by the blockings of CD4+ T cells or macrophages." (PMID 36068198, 2022). "The single-cell transcriptome data revealed that TNBC tumor samples with high PANX1 expression had lower infiltration of B cells, CD4+ T cells, CD8+ T cells, myeloid cells, NK cells, and NK T cells and higher infiltration of cancer-associated fibroblasts (CAFs), plasma cells, and Tregs." (PMID 35884429, 2022).
tumor (continued). "For cTreg and Tr1 cells, CD8+T and CD4+ T cells remained in similar frequencies in the lymph nodes of tumor animals, treated or not with anti-CD29, ∼25% for both subsets." (PMID 35860556, 2022). "Additionally, CD4+ T cells indirectly mediate the activation and maturation of DCs, which activate CD8+ T cells either by cross-presenting tumor antigens or by producing effector cytokines such as IFN-γ and TNF-α." (PMID 35759090, 2022). "Additionally, the expression of HSP90AA1 and HSP90AB1 was positively correlated with tumor purity; and the expression of HSP90AA1 was positively related to CD8+ T cells, macrophages, and neutrophils, but negatively correlated with CD4+ T cells." (PMID 35845599, 2022). "We could demonstrate spontaneous T-cell responses to 5/18 (28%) mutated gene variants, and further analysis of the TCR repertoire of neoantigen-specific CD4+ and CD8+ T cells revealed TCR clonotypes that were expanded in both blood and tumor tissue." (PMID 35361728, 2022). "As indicated in these reports, mesenchymal marker expression increased, the infiltration of suppressive immune cells in the tumor microenvironment, including CD3+ CD8+ PD-1+ T cells, CD4+ FOXP3+ Tregs, and M2 macrophages, increased, and the infiltration of cytotoxic T cells decreased." (PMID 35463314, 2022). "In our study, HNRNPA2B1 was positively correlated with activated CD4+ memory T cells and activated myeloid dendritic cells, implying that HNRNPA2B1 may enhance the efficacy of immunotherapy through regulating the tumor-infiltrating immune cells." (PMID 36189296, 2022). "Tumor infiltrating immune cell profile analyses also revealed the reduction of immuno-suppressive CTLA-4+CD8+ cells and CD4+CD25+Foxp3+ Tregs, whereas the percentage of tumor infiltrating cytotoxic CD8+ T cells and the ratio of M1/M2 macrophages increased in nCHI3L1 Ab treatment group." (PMID 34987649, 2022). "Although the difference was not significant, with the increase of tumor grade, clinical stage, T-stage, and N-stage, the abundance of T cell CD4 memory activation and monocytes increased." (PMID 35422890, 2022). "While the major focus of immunotherapies has largely been alleviating the cell-intrinsic defects of CD8+ T cells in the tumor microenvironment (TME), amending the relationship between tumor specific CD4+ T cells and CD8+ T cells has started driving attention as well." (PMID 36248808, 2022). "The ratios of γδ T/CD4+ and γδ T/CD8+ T cells were significantly increased in the spheroids compared to those outside of the spheroids, supporting that γδ T cells proliferate and infiltrate tumour spheroids more efficiently than CD4+ and CD8+ T cells." (PMID 35731974, 2022). "LAG-3 inhibits the anti-tumor effect of anti-PD-1 and anti-LAG3 therapy in HL by inhibiting the CD4+ T cell responses; chemotherapy with ABVD (doxorubicin, bleomycin, vinblastine, and dacarbazine) shows little therapeutic effect with a higher infiltration of LAG-3+TILs." (PMID 36077354, 2022). "Furthermore, FACS analysis revealed that combinational treatment didn’t significantly change the amount of tumor-infiltrating CD8+ and CD4+ T cell." (PMID 36457047, 2022). "The results showed that, compared with the control group, the SGR-EA group showed promoted infiltration of CD8+ T cells and CD4+ T cells in the tumor tissue, but it was not statistically significant." (PMID 35935838, 2022). "As a result, we observed the expression of CD4 and CD8 was significantly increased in FFPE tumor tissues from patients of XNSG compared with XSG; while in FFPE tumor tissues from patients of XHSG, we observed the expression of CD4 and CD8 was significantly increased, compared with XHNSG." (PMID 36175412, 2022). "First, we compared the frequency of DP CD4+ and DP CD8+ TILs in HNSCC and CRC tumor samples." (PMID 35439168, 2022).
tumor (continued). "The number of splenic CD3+ CD4+ T cells in the COMB group drastically increased in comparison with control tumor-bearing mice, whereas no significant changes were observed in CD3+ CD8+ T cells." (PMID 35681703, 2022). "Furthermore they are considered APCs, thus, this function is also involved in anti-tumour immunity by presenting antigens to CD4+ and CD8+ T cells and developing an immune response within the tumour microenvironment." (PMID 35406451, 2022). "CD4+CD25+ Treg cells can also affect the function of dendritic cells by downregulating the activity of NF-κB, thereby significantly reducing the DC-mediated tumor cell-killing effect." (PMID 36553542, 2022). "I.p. administration of IL-36 agonists was seen to be associated with a significant increase in CD4+ and CD8+ T cells within the tumour, whilst no significant alterations of these immune populations were observed in IL-36Ra treated mice." (PMID 35365751, 2022). "Suppression of blastogenesis and proliferation of CD4+ T cells by highly polyreactive anti-Face-2 mAbs (e.g., TFL-006 and TFL-007) point out that they can be potential immunotherapeutic agents for controlling tumor progression." (PMID 35214796, 2022). "After 7-day treatment of toripalimab (PD-1 monoclonal antibody, 10 μg/mL) or isotype IgG4 antibody as negative control, we investigated the ratio of CD8+/CD4+ T cells and the effect of tumor killing by fixable viability stain (FVS)." (PMID 36544542, 2022). "Besides its impact on tumor cell signaling, sotorasib was also found to restore an efficient immune tumor response as evidenced by increased T-cell infiltration and immune effectors including macrophages, CD103+ dendritic cells and CD4+/CD8+ T-cells." (PMID 35251972, 2022). "Furthermore, anti‐PD‐L1‐DOX‐R848‐MIP‐3α/TKNP‐treated mice showed increased intratumoral infiltration of CD4+ and CD8+ T cells and enhanced level of circulating and tumor‐infiltrated cytokines for better antitumor effect." (PMID 37693071, 2022). "FLASH increased recruitment of CD3+ T lymphocytes from the peripheral tumor edge into the tumor core, and both CD4+ and CD8+ cells were also increased in the core, which might account for the high tumor control for mice irradiated with FLASH." (PMID 36291585, 2022). "Notably, the infiltration of effector cells of anti-tumor immune response was higher in the AAMRGS-low group, such as CD8+ T cells, activated memory CD4+ T cells, activated NK cells, monocytes, and mast cells." (PMID 36582227, 2022). "Hypoxia, low glucose, and low pH induces the directional differentiation of Tregs, MDSCs and M2 macrophages, and at the same time inhibites the functions of NK cells, CD4(+) T cells, CD8(+) T cells and DCs, and finally forms an immunosuppressive microenvironment, leading to tumour progression." (PMID 36578477, 2022). "Interestingly, in addition to the indirect critical role of CD4+ T cells during antitumor response, effector CD4+ T cells are able to recognize and kill directly MHC-II+ tumor cells." (PMID 35008422, 2022). "The tumor cell growth inhibition induced by cryo-thermal CD4+ T cells was much stronger than that induced by tumor-bearing CD4+ T cells, but via neutralization of IFN-γ, cryo-thermal CD4+ T cells promoted the growth of tumor cells." (PMID 35874660, 2022). "Furthermore, the cytotoxic activity of CD8+ and CD4+ CAR-T cells and their capacity to eradicate tumor cells have been evaluated." (PMID 35008422, 2022). "AZD5582 potently activates the NFκB pathway, but does not induce apoptosis in non-tumor cells and shows a modest off-target effect in host gene expression in CD4+ T cells treated ex vivo when compared with a stabilized Ingenol-B derivative (GSK445A)." (PMID 35891551, 2022). "Furthermore, on the 5th day after injection, an increase in the percentage of CD4+ and CD8+ cells in tumor tissue from mice treated with DC-based vaccines was observed." (PMID 35372586, 2022).